TGFB1 (transforming growth factor beta 1)
Diseases named in the same sentence as TGFB1 in open-access papers (continued):
Sharing a sentence is not in itself a finding about the gene and the disease.
cancer (continued). "Remarkably, our immunoblotting data suggested an overexpression of TGFβ1 in cocultured IHH hepatocytes and cancer cells." (PMID 35267627, 2022). "Adding further to the pathophysiological relevance of our study, we note that collective invasion, which was triggered by TGFβ1 in TKA organoids, accurately reflects the predominant mode of stromal infiltration in most carcinomas." (PMID 35075245, 2022). "The top three growth factors with strong correlations with OSM in most cancers were HGF, PDGFB, and TGFB1." (PMID 34702277, 2021). "TGFB1 was reported to induce the expression of THBS1, resulting in stimulating migration of cancer cells and driving the expression of MMP3 (matrix metalloprotease 3) via integrin signaling, conducive to OSCC intrusion." (PMID 35237609, 2021). "The cancer database analyses must be considered with caution, yet they suggest that MIR100HG and TGFB1 present similar predictive values in the prognosis of certain cancers." (PMID 33941855, 2021). "We repeated a similar experiment by co-culturing HT29 cancer cells with hepatocytes in the presence of LSKL (Leucine-Serine-Lysine-Leucine), an inhibitor of TSP1-mediated TGFβ1 activation." (PMID 34376784, 2021). "TGFβ1-dependent ARP2/3 and vimentin expression in cancer cells were attenuated in the presence of RUNX1 inhibitor (Ro5-3335)." (PMID 34376784, 2021). "Noteworthily, cohesin is reported responsible for EMT/MET via chromatin interactions of mesenchymal genes TGFB1 and ITGA5 loci, implying the significance of conformational changes in cancer metastasis process." (PMID 34689165, 2021). "Several studies have demonstrated that resveratrol can modulate the expression of miR-663 and its target the transforming growth factor beta 1 (TGF1) transcript, in inflammation and inflammation-related cancers." (PMID 34942997, 2021). "Surprisingly, silencing endogenous TGFB1 in PDAC and TNBC-derived cancer cells with known autocrine TGFβ1 production allowed exogenous TGFβ1 to elicit a more pronounced migratory and growth-inhibitory response." (PMID 33802809, 2021). "First, we grouped the 9736 TCGA cancer cohorts into high or low RNA expressions of EGFR, mTOR, NOS2, TGFB1, mTOR, and FGFR1 and compared the survival of cohorts from the two groups." (PMID 33842373, 2021). "This is in line with other studies that demonstrate the role of TGFβ1 signaling in driving COL11A1 expression, EMT phenotype, and cancer invasion and metastasis." (PMID 33668097, 2021). "MMP9 promotes TGFβ1 induced EMT leading to increased migration and invasion capacity of thyroid, lung and esophageal squamous cancer cells." (PMID 33809973, 2021). "Using cultured cell models of cancer, we have shown that S100A10 is regulated by Smad4-dependent TGFβ1-mediated signaling and FOXC2-mediated PI3K signaling." (PMID 34944416, 2021). "Immunosuppressive cytokine markers TGFB1 and IL10 were significantly enriched in the EMT-high group of almost all cancer types compared to those in the EMT-low." (PMID 35096592, 2021). "Analysis of cytokines showed significant enrichment of immunosuppressive cytokines—TGFB1 and IL10—in the EMT-high group of almost all cancer types." (PMID 35096592, 2021). "To identify unequivocally in which tissue compartment the expression of TGFβ1 is upregulated, we performed fluorescence in situ hybridization (FISH) assay for TGFβ1 combined with cancer cell-specific (anti-Cytokeratin 20) staining." (PMID 34376784, 2021). "TGFβ1 is not only a key player in fibrosis in some organs, but it also acts as the TME and as a carcinomatous transformation regulator in cancer pathophysiology." (PMID 34884420, 2021).
cancer (continued). "The mechanism proposed here is that metformin inhibits the TGFB-1 pathway, thus decreasing the TGFB-1-induced epithelial-mesenchymal transition, N-cadherin, and MMP, all involved in cancer metastasis." (PMID 34440224, 2021). "Transforming growth factor beta 1 (TGF-β1) is an immunosuppressive cytokine that induces regulatory T cell (Tregs) differentiation and is involved in immune evasion mechanisms in cancer." (PMID 34195245, 2021). "Resveratrol has shown a unique ability to modulate multiple signaling pathways including Wnt, TGFβ1, Notch and STAT in various types of cancer." (PMID 33471184, 2021). "Of note, both TGFβ1 and PAI-1 were also found to be the putative target of HuR in human cancer cells since both of them contain conserved AREs in their 3′-UTR." (PMID 32478392, 2020). "To further investigate the effect of METTL3 on EMT, we treated cells with 10 ng/mL TGFβ1, which has been considered to be the major EMT inducer in cancer cells." (PMID 31991845, 2020). "Both qRT-PCR and Western blot analysis showed that the expression of TGFβ1 and METTL3 increased in high lung metastasis potential cancer cells compared with that in the parental cells." (PMID 31991845, 2020). "Together, our research demonstrated that m6A performed multi-functional roles in TGFβ1 expression and EMT modulation, suggesting the critical roles of m6A in cancer progression regulation." (PMID 31991845, 2020). "In this study, we focused on building GRCs using the single cell RNA sequencing (scRNA-seq) data collected from Cook and Vanderhyden (2019) for four cancer cell lines (A549, DU145, MCF7, and OVCA420) treated with EGF, TGFB1, and TNF." (PMID 32391378, 2020). "Together, our data suggest that m6A performs multi-functional roles in the TGFβ1 expression and EMT modulation of cancer cells." (PMID 31991845, 2020). "Platelets are the main source of transforming growth factor-beta 1 (TGF-β1) in the circulation, which plays a crucial role in cancer metastasis." (PMID 31968611, 2020). "We demonstrated that conditioned medium (CM) from macrophages exposed to apoptotic cancer cells inhibits the TGFβ1-induced epithelial–mesenchymal transition (EMT), migration, and invasion of cancer cells." (PMID 30842627, 2019). "In PDAC tissues, cancer cells and macrophages are likely a main source of PDGF and TGFβ1 with distinct effects on PaSC proliferation, migration and production of ECM and cytokines." (PMID 31849712, 2019). "The TGFβ1 pathway is likely to contribute to the maintenance of established tumors, because disruption of TGFβ1/SMAD signaling in human PDAC cells influences cancer cell growth in vitro and tumorigenesis in xenografts." (PMID 31109321, 2019). "The DCGs, including GART, TGFB1, ITGA2, SLC16A5, SOX9, and MMP7, were investigated across 12 cancer types." (PMID 29843204, 2019). "The transforming growth factor beta 1 (TGF-β1) also promotes aggressiveness and the invasion of various cancer cells." (PMID 31728117, 2019). "In the current paper, we demonstrated that TGFβ1 can induce EMT and promote the acquisition of cancer stem-like properties in a group of TGFβ1-sensitive NSCLC cells with upregulation of VEGFR3 expression." (PMID 29995950, 2018). "Molecular method was based on the analysis of selected genes expression related to hypoxia (HIF1A, ANGPTL4, TGFB1, VEGFA, ERBB3, CA9) or specific for inflammation in hypoxic sites (CCL2, CCL5) at various time points after CT26 cancer cells inoculation." (PMID 30412628, 2018).
cancer (continued). "DVL2 and TGFB1 have repeatedly been shown to act as inductors of epithelial-to-mesenchymal transition (EMT), one of the hallmarks of cancer progression." (PMID 30366472, 2018). "Serum levels of cancer markers (AFP and GGT), TGFβ1, and liver enzymes (ALT, AST, and ALP) were significantly higher in the CSC-Ex group, followed by the PBS group as compared to the normal group." (PMID 30224923, 2018). "Antibodies for Slug, TGFβ1, and basic leucine zipper ATF-like transcription factor 2 (SARI) reacted negatively in all carcinomas." (PMID 29976164, 2018). "By linking leptin signalling to the established TGFB1 pathway of metastasis / EMT, this study gives a direct mechanism by which leptin can contribute to the poorer outcomes of obese cancer patients." (PMID 28542577, 2017). "In this study, we chose to focus on the most prominent isoforms of activin and TGF-β in CRC, activin A and TGFB1, respectively as they are the two cancer dominant isoforms." (PMID 28717230, 2017). "To evaluate the importance of TGFβ1 in CAF-derived exosomes supporting a pre-metastatic niche in vivo, we mixed SKOV-3-Luc cancer cells and CAF, and co-injected them into BALB/c nude mice, with or without an intraperitoneal injection of anti-TGFβ1." (PMID 29221185, 2017). "The upstream regulators of these functions were predicted to involve the growth factors TGFB1, EGF, HGF and IGF1, which have known roles in activating these cancer progression pathways." (PMID 27965461, 2017). "These genes belong to relevant intracellular signaling pathways in cancer such as PI3K-Akt (COL4A2, MYC, PDGFA, SPP1), proteoglycans (HIF1A, MYC, PLAUR, TGFB1), and Hippo (CTGF, MYC, NF2, TGFB1)." (PMID 29075357, 2017). "TGFβ1 has been shown to be a driver of the epithelial-to-mesenchymal transition (EMT) process, also termed “mesenchymalization” of carcinoma cells." (PMID 29088859, 2017). "In order to elucidate the potential role of lovastatin in cancer gene expression, lovastatin-treated HuH-28 and RBE cells were harvested and qPCR was used to quantify expression of integrin β3, TGFβ1, ICAM-1, and COX-2." (PMID 26517522, 2016). "Thus, TGFβ1 can induce some non-fibroblast cells, including adipocytes and circulating bone-marrow-derived suppressor cells, to trans-differentiate into cancer-associated myofibroblasts." (PMID 27515461, 2016). "In certain cancers, such as hepatocellular carcinomas, Treg express significantly more GARP, which correlates with elevated TGFβ1 blood levels." (PMID 27054568, 2016). "It is well established that TGFβ1 plays important roles both in cancer EMT and cancer stem cell (CSC) properties, and is up-regulated in PCa after androgen deprivation therapy (ADT)." (PMID 25483103, 2015). "In out study, knockdown of ZEB2NAT reversed CAF-CM induced ZEB2 protein level and partially inhibits the CAF-CM induced cancer cell invasion, indicating that ZEB2NAT is one of the essential TGFβ1 downstream components involved in EMT and cancer cell invasion." (PMID 26152796, 2015). "TGFB1 itself and its receptors (TGFBR1 and TGFGR2) are aberrantly regulated by promoter methylation in various cancers including gastric, breast, lung, and ovarian." (PMID 25814785, 2015). "Based on the result of the IPA analysis, 5 proteins (TGFβ1, PI3K, Akt, mTOR and PTEN) related to specific functions, such as proteins synthesis, cellular functionsand cancer, were selected for verification." (PMID 25793716, 2015). "Cancer-related genes with significant up-regulation in all ATCs included MYC, mTOR, PRKCA and TGFB1." (PMID 26680454, 2015). "Since EMT is generally associated with a migratory phenotype that is indispensable for cancer metastasis, we performed wound-healing assays in MCF-7 cells treated with TGFβ1 or TGFβ1/EGF." (PMID 25277187, 2014).
cancer (continued). "To further examine the underpinnings of these observations, we investigated the relationships among SRC, TGFB1 and PPARB/D expression levels in human carcinomas from various organs." (PMID 24203162, 2014). "Expression of TGFβ1 and HGF in inflammatory cells was also shown in regions adjacent to cancer nests." (PMID 24137336, 2013). "The role of TGFβ1-signaling pathway in the pathogenesis of SCC and other cancers is complex due to the diverse biological processes that are regulated by TGFβ1 and the cell type and context dependence of specific responses." (PMID 23326666, 2012). "Transforming growth factor beta 1 (TGF-beta-1), I-6/10, IGF, and gamma glutamyl transferase (GGT) enzyme levels are proposed cancer biomarkers." (PMID 24281040, 2010). "We have evaluated the ability of a small molecule TGFβ inhibitor, TβRI-KI, to block the EMT process and subsequent cancer stem cell formation by TGFβ1 and doxorubicin treatment in 4T1 cells in vitro." (PMID 20442777, 2010). "Network 2 has TGFB1 and IL4 driving several genes known to be involved in cancer development but also known to negatively regulate potentially tissue destructive immune responses." (PMID 18267009, 2008). "Epithelial Mesenchymal Transition (EMT) was another pathway depleted upon knockout, and subsequent analysis revealed a significant correlation between NNMT and EMT-related genes (VIM, CDH2, FN1, TGFB1, and ZEB2) in both the Cancer Cell Line Encyclopedia (CCLE) panel and patient data." (PMID 41997904, 2026). "Genes NOG, TGFB1, VIRMA, and SRC were over-expressed in cancer." (PMID 40724805, 2025). "Despite the importance of G9a in fibrosis and cancer, the impact of matrix stiffness on G9a expression and signaling in response to TGFβ1 is not known." (PMID 40661662, 2025). "Furthermore, we investigated two promising molecules AMD3100 and D4476 using synergistic approach for targeting TGFβ-1 and CXCR4 to be explored as better anti-cancer therapeutics in future." (PMID 41348904, 2025). "Finally, we confirmed that the expression levels of the top immunosuppressive genes, EBAG9, PVR, TGFB1, B7-H3, TNFRSF14, and PD-L1, were significantly higher in the high-p62 group than in the low-p62 group in most cancers." (PMID 41291343, 2025). "Furthermore, SERPINE1 interacts with various proteins such as TGFB1, FN1, MMP1, influencing cancer cell adhesion, and motility." (PMID 39817507, 2025). "Our scRNA-seq clarified that TGFB1 was ubiquitously expressed in non-specific stromal cells including CAFs but weakly in cancer cells of both CRC and GC." (PMID 40075643, 2025). "Similarly, ZNF668 was positively correlated with PVRL2 (Nectin-2), CD276 (B7-H3), TGFB1, and multiple members of the TNF receptor superfamily, including TNFRSF4 (OX40), TNFRSF18 (GITR), and TNFRSF25, in the vast majority of analyzed cancers." (PMID 41614761, 2025). "Additionally, DCIS-associated MECs secret transforming growth factor beta 1 (TFGβ1), which activates the TGFβ/Smads signaling pathway, promoting epithelial–mesenchymal transition (EMT) and further facilitating cancer progression." (PMID 40563575, 2025). "Also, NRP1 contributes to TGFβ1‐induced EMT and metastasis in NSCLC by binding directly to the TGFβRII receptor, further illustrating its role in aggressive cancer behaviors." (PMID 39083441, 2025). "INHBA/TGFB1 complex activates SMAD2/3 and improves stem cell characteristics in cancer cells." (PMID 38881758, 2024). "In addition, platelets are the main producer of TGFβ1, which can lead to cancer invasion by launching epithelial‐mesenchymal transition (EMT) of cancer cells." (PMID 38348939, 2024). "It was found that the core targets such as PTGS2, CXCL8, TGFB1, and STAT3 were mainly enriched in the pathways related to cancer and several inflammatory factors, and that tretinoin and PTGS2 as well as tretinoin and PTGS2, CXCL8, and STAT3 had strong binding activities." (PMID 39224778, 2024).
cancer (continued). "The scRNA-seq data from four different cancer cell lines (A549, DU145, MCF7, and OVCA420) revealed that signaling pathways known to drive EMT- like TGFβ1, EGF, and TNF- converge on NF-κB and FOSL1, before initiating the expression of typical EMT master regulators such as STAIL, TWIST, and ZEB." (PMID 38856747, 2024). "In addition, TGFβ1-dominant cancers such as CESC, GBM, and HNSC showed a high correlation between CD59 and TGFβ1, leading to suppression of cytotoxic T cell activity." (PMID 39518137, 2024). "Additionally, we found increased TGFB1 and SMAD3 RNA levels, key components in the TGF-β1/SMAD signaling known to promote EMT and metastasis in cancer." (PMID 39398277, 2024). "Furthermore, the expression of CD276, MICB, PVR, TGFB1, and TGFBR1 displayed high correlations with TUBA1B expression in most cancers." (PMID 38589634, 2024). "Additionally, transforming growth factor beta-induced protein (TGFBI, or βig-H3) is a matrix protein determined by TGFβ1 and secreted into ECM by various cancers." (PMID 36906534, 2023). "CFP1 upregulated expression of β-catenin, LEF1, TCF1/TCF7, c-MYC, TGFBR3, and TGFB1, and the cancer-promoting effects of CFP1 were not completely repressed by pathway inhibitors." (PMID 37735441, 2023). "In summary, these results suggest that the TGFB1 and IL6ST modules may have broader effects in cell communications in multiple cancer types." (PMID 38054018, 2023). "Next, these SCFAs were tested with TGFβ1, a strong EMT promoter in cancer." (PMID 37766669, 2023). "EMT-inducing factors such as TGFβ1 and IL6 were upregulated in H69 following direct interaction (cluster 1), suggesting that multiple concomitant pathways are activated in cancer cells in our system." (PMID 36936987, 2023). "We demonstrate that only after direct contact with fibroblasts the cancer cells start an extensive reprogramming process that results in the upregulation of EMT inducers, such as TGFβ1, and subsequent regulation of genes facilitating interaction with the ECM and invasion." (PMID 36936987, 2023). "Notably, immune checkpoints TGFB1 and CD276 were significantly positively correlated in 25 types of cancers." (PMID 37504302, 2023). "The role of PURA in cancer, in particular, in transcriptional regulation, is complex and context dependent; for example, PURA can function as a transcriptional activator for some genes, including TGFβ1,53 TNFα,54 and β2-integrin." (PMID 37149929, 2023). "Among these, only let-7a-5p showed a negative correlation with the expression of TGFβ1 and TGFβ-R1 as well as the cancer cell migration and metastasis." (PMID 35406397, 2022). "In addition, we found that ecm myCAFs can interact with TAMs via TGFB1-TGFBR1/2 pairings, which have been shown to promote cancer progression." (PMID 35538548, 2022). "Transforming growth factor beta 1 (TGF-β1), tumor necrosis factor alpha (TNF-α), and hypoxia cooperate in the triggering of EMT both in cancer and fibrosis, converging in the induction of Snail activity through different mechanisms including the activation of transcription factor NF-kB." (PMID 36291542, 2022). "Moreover, the upregulation of ARP2/3 in VCO-dependent cancer cells relies on runt-related transcription factor-1 (RUNX1), which is expressed upon the induction of transforming growth factor beta-1 (TGF-β1)." (PMID 36119528, 2022). "It was also found that TGFB1 induces EMT during tumorigenesis and metastasis in cancer." (PMID 35593122, 2022). "In The Cancer Genome Atlas (TCGA) database, we found MDK is the highest upregulated growth factor in different types of cancer, even higher than that of established growth factors such as VGF, EGF, and TGFB1." (PMID 35487917, 2022). "This work shows that the compounds in GTF can play a role in bone protection by stably combining with IL6 and TGFB1, which may also be one of the reasons that GTF can prophylax and treat cancer-related pain." (PMID 35872837, 2022).